CD1A (CD1a molecule)
Diseases named in the same sentence as CD1A in open-access papers (continued):
Sharing a sentence is not in itself a finding about the gene and the disease.
tumor (continued). "High-CD1a levels were significantly associated with worse EFS (p = 0.012), and high-CD4 showed numerical differences with better EFS (p = 0.06) in luminal-B tumours." (PMID 38473874, 2024). "The results indicate strong confounding between CD1a-DCs and LN metastasis and suggests the theory that CD1a-DCs are developed from monocytes at tumor sites." (PMID 39684473, 2024). "In this context, an anti-CD1a mAb named CR2113, has been demonstrated to induce potent ADCC in CD1a-expressing cell lines and T-ALL primary samples in vitro, which translated in anti-tumor activity against CD1a-expressing xenografts." (PMID 36624522, 2023). "In IBC, the higher numbers of CD1a+ and mature CD83+ DCs are associated with smaller tumor size, higher overall survival and a lower risk of relapse in triple-negative BC after neoadjuvant chemotherapy without pathological complete response." (PMID 37373062, 2023). "The enhancement of IL-37 expression by HCC cells is accompanied by an increase in the levels of CCL3 (chemokine (C-C motif) ligand 3) and CCL20, which further promotes the recruitment of CD1a+ dendritic cells (DCs) in the tumor infiltrate." (PMID 37298214, 2023). "CD1a+ immature DCs (iDCs) were predominantly present in the tumor bed, while DC-Lamp+ mature DCs were observed to be exclusive in the tumor stroma." (PMID 35619702, 2022). "A high number of BDCA2+ DCs was correlated with tumor invasion depth and was inversely proportional to the number of CD1a-positive cells in EBVaGC." (PMID 35311157, 2022). "The in vivo anti-tumor activity of CD1a x CD3ε against CD1a-expressing T-ALL cells was investigated." (PMID 35740552, 2022). "High IL-37 expression by HCC tumor cells is associated with upregulated levels of CCL3 and CCL20 and increased recruitment of CD1a+ dendritic cells (DCs) in tumor infiltrations." (PMID 36551790, 2022). "With the aim to build a therapeutic platform against T-ALL, we developed a novel asy metric BTCE that simultaneously binds a unique epitope of CD1a and CD3ε (CD1a x CD3ε) to recruit and trigger a powerful T-cell-mediated anti-tumor response." (PMID 35740552, 2022). "The analysis of a cohort of CRC patients revealed a high CD1a+/DC-LAMP+ tumor-infiltrating DC ratio, indicating that there were more iDCs than mature DCs in the CRC tumors." (PMID 35619702, 2022). "The inhibited appearance of CD1a by tumor cells or dexamethasone promotes the generation of anti-inflammatory moDCs." (PMID 36194602, 2022). "Consistently with these in vitro data, CD1a x CD3ε led to a significant anti-tumor activity and survival advantage of treated animals in a mouse model of human T-ALL reconstituted with human immune effectors." (PMID 35740552, 2022). "With regard to type of metastasis in SLN, we observed that CD1a+ DCs tended to decrease their numbers in distant area from tumor-free SLNs, SLNs with micrometastases to SLNs with macrometastasis (p = 0.055)." (PMID 35955602, 2022). "Macrophages and CD1a + DCs (DC_c3_CD1A) were significantly enriched in tumors compared with paired non-tumor tissues, while monocytes, CD1c+ DCs (DC_c1_CD1C), and cDC1 DCs (DC_c2_XCR1) showed the opposite trend." (PMID 35347134, 2022). "CD1a+ cells at tumor edge correlated with DC-LAMP+ (R = 0.64, p < 0.001) and CD1c+ cells (R = 0.33, p < 0.010) at the same location." (PMID 35955602, 2022). "In our study, we have not observed statistically significant differences in the spatial distribution of CD1a+ DC subpopulation, but higher numbers of these cells were found mainly within the tumour." (PMID 33919875, 2021). "An infiltration of CD1a+ DCs was observed in all 57 cases, with various densities in areas adhering to or adjacent to tumor cells." (PMID 34461859, 2021). "CD1A protein expression in tumor as well as immune cells was independent from corresponding tumor grading but highly correlated with the occurrence of an early post-surgical relapse." (PMID 33953302, 2021).
tumor (continued). "As the early relapse group is enriched for high grade and undifferentiated tumors, we also performed chi-square test for correlation analysis between CD1A protein expression and tumor grading." (PMID 33953302, 2021). "Similar results suggesting a significant effect on survival after immature CD1a+ DCs infiltration into tumor compared to mature DCs have been reported for several body organs." (PMID 34461859, 2021). "This analysis revealed that immunohistochemical detection of CD1A expression in tumor as well as immune cells respectively is independent from grading as G1/G2 vs. G3/G4 tumor (p > 0.05)." (PMID 33953302, 2021). "The factors significantly correlated with OS were tumor subsite, T stage, N stage and infiltration of CD1a+ DCs (P = 0.046, P = 0.008, P = 0.003, P = 0.035, respectively)." (PMID 34461859, 2021). "We think that an increase in CD1a+ cell count attracted to the tumour environment has a capability to initiate an immune response to the malignancy in the host organism, which results in a better prognosis." (PMID 33919875, 2021). "Taken together, the past and present findings show that the relationship between tumor-infiltrating CD1a+ DCs and clinical outcomes in patients with malignancies remains controversial." (PMID 34461859, 2021). "Herein, the SA method showed a decreasing positive DCs number in poorly differentiated tumours for peritumoral CD1a+ cells, and the UA method presented the opposite result." (PMID 32134901, 2020). "Regarding DC positioning inside the tumor zones, as is the case with T cells, mature CD83+ DCs stay predominantly outside of the tumor center, with immature CD1a+ DCs recruited into the tumor." (PMID 32781527, 2020). "In the present study, a high number of BDCA-2-positive DCs was correlated with tumor invasion depth and was inversely proportional to the number of CD1a-positive cells in EBVaGC." (PMID 33198173, 2020). "In this study, CD1a+ cells were registered almost exclusively in close contact with tumour epithelium." (PMID 33153211, 2020). "TdT and CD1a appeared to be very similar, with both the highest expressions in type B, moderate expressions in normal thymus and tumor‐adjacent tissues, and marginal expression in type A and type TSCC." (PMID 31967407, 2020). "A decreasing of peritumoral CD1a+ cells were observed in advanced tumours stages (stage III/IV) (P=0.0901, SA method; P=0.0627, UA method)." (PMID 32134901, 2020). "CD1a+ dendritic cells occurred in relatively low densities and were predominantly counted in tumour epithelium." (PMID 33153211, 2020). "As for immunohistochemistry, all neoplasms stained positively for CD1a, CD207 (Langerin) and S100; inconstant was the stain for CD34 and CD68 (approximately 60%)." (PMID 32825016, 2020). "For peritumoral CD1a+ cells, the number of positive DCs decreased in poorly differentiated tumours using the SA method, and the opposite happened with the use of the UA method." (PMID 32134901, 2020). "Immunohistochemistry was used to double-stain two adjoining sets of tissue microarrays from pre-RT (radiotherapy) tumour resection samples for CD1a/CD20 and CD45RO/CD4." (PMID 33153211, 2020). "The immune infiltrate in pre-treatment tumor samples of both patients was composed of immature T cells expressing TdT, CD1a and CD5, CD4 and CD8." (PMID 31639039, 2019). "We compared the numbers of CD3+ T cells, CD20+ B cells, and CD1a+ dendritic cells per mm2 area in tumor-invaded nodes (positive) to tumor-free lymph nodes (negative)." (PMID 30155518, 2018). "In our study, we investigated tumour-infiltrating CD1a+ DCs and concurrently circulating DCs, mDC1shigh and pDCshigh." (PMID 28913366, 2017). "It was observed that the effect on blocking the decrease of CD14 and CD1a appearance was restricted to microvesicles-free supernatant, thus eliminating the role of these tumor microvesicles at least on the CD14 and CD1a modulation." (PMID 27088097, 2016).
tumor (continued). "The Langerhans cells diffusely infiltrated in the dermis and the tumor cells were positive for CD1a and S-100 expression." (PMID 26942568, 2016). "In the whole slide specimens, tumor infiltration by APCs was associated with poorer 5 yr-EFS, including CD1a+ DCs (28.3% vs. 83.9%, p = 0.001) and CD68+ macrophages (45.5% vs. 84.4%, p = 0.032)." (PMID 27456063, 2016). "Analysis revealed that the tumor cells were immunopositive for vimentin, microphthalmia transcription factor, S100, CD1a, CD10, CD63, and folliculin, but immunonegative for cytokeratin, α-smooth muscle actin, HMB45, Melan-A, and PNL-2." (PMID 27871249, 2016). "Instead, of the studied types of tumor infiltrating immune cells, only intratumoral CD1a+ dendritic cells (p = 0.012) and neutrophils (p = 0.027) showed significant correlation with serum 25(OH)D levels." (PMID 27819306, 2016). "Based on these results, LCs and CD1a+ dDCs seems suitable targets for targeted anti-tumor immunotherapy using soluble peptides in the presence of TLR3 ligands." (PMID 26605924, 2015). "Alternatively, support for LCH as a neoplasm is based on publications that have shown clonality of the CD1a+ cells in LCH using the human androgen receptor assay and BRAF mutation studies." (PMID 25343480, 2014). "Langerin staining, accompanied by S100 and CD1a staining, confirmed the presence of Langerhans cells in the tumour." (PMID 24555881, 2014). "Immunocytochemical stains were performed on the cell block and the tumor cells stained positively with CD1a, S-100, and CD68." (PMID 24587931, 2014). "Langerhans cells positive for langerin, S100, and CD1a were seen in the epithelial islands of the tumour." (PMID 24555881, 2014). "By immunohistochemistry, the tumor cells were positive for CD1a, S-100 protein and largerin strongly and diffusely." (PMID 23388086, 2013). "In the present case, we found that the tumor cells exhibited remarkably cellular atypia and higher mitotic activity with co-expression of CD1a, S-100 protein and langerin." (PMID 23388086, 2013). "In our case, the tumor cells strongly expressed CD1a, S-100 protein and langerin, which were Langerhans cell-specific marker, arguing against other cutaneous hematological neoplasma." (PMID 23388086, 2013). "Most importantly, combined STAT3 and p38 inhibition supported a shift from CD14+ monocyte-like cells to CD1a+ DC in metastatic melanoma single-cell suspensions, indicating a potential for improved DC differentiation in the tumor microenvironment." (PMID 24324467, 2013). "The diagnostic factors of LCS includes: typical histological features of tumor cells with characteristics of Langerhans cells; typical immunophenotype, such as, Langerin, CD1a, S-100; and ultra-structure characteristics, Birbeck granules within the cytoplasm." (PMID 22889043, 2012). "The tumor cells showed intense membrane staining for CD1a, strong granular cytoplasmic staining for langerin (CD207), strong staining for S100 and CD4." (PMID 23006414, 2012). "The tumor cells expressed CD1a, Langerin (CD207), S-100 protein, CD68 and vimentin, and did not express pan-T or B cell markers and epithelial markers." (PMID 22889043, 2012). "CCR6+, CD1a+ and Langerin+ tumor-infiltrating DC were occasionally identified in serial tissue sections from the same tumor (not shown)." (PMID 21624121, 2011). "The number of CD1a+ immature DCs per high-power field within the tumour tissue ranged from 1-24 cells, with mean and median numbers of 12 and 7, respectively." (PMID 20969772, 2010). "In all samples, CD1a+ cells with dendritic morphology were found randomly distributed throughout the entire tumour beds." (PMID 20969772, 2010). "The observed numbers of immature CD1a+ DCs in the tumour environment was much higher than in normal kidney tissues, suggesting increased homing and infiltration of immature DCs by the tumour." (PMID 20969772, 2010).
tumor (continued). "All specimens contained cells positive for CD68, CD163, S100 and CD1a in epithelial tumor tissue and tumor stroma." (PMID 18047662, 2007). "Although the number of CD1a-positive DCs are almost the same as that of CD83-positive DCs in the invasive margin of the tumour, CD1a-positive DCs are mostly scattered and rarely form clusters with lymphocytes." (PMID 17026740, 2006). "Analyses were performed between CD1a and tumour size, grade, nodal status, Ki-67 (MIB-1), presence/absence of metastases, presence/absence of recurrence, presence/absence of lympho-vascular invasion." (PMID 12888826, 2003). "The CD1a+ cells were present in the stroma between islands of tumour cells and in more differentiated tumours were situated around the ductal formations." (PMID 11870535, 2002). "Additionally, CD1a+ dendritic cells can migrate from the tumor exterior toward tumor interior along chemokines gradients to increase pool of immature DCs there." (PMID 41410751, 2025). "Additionally, patients with PD‐L1 amplification showed reduced tumor infiltration with CD1a+ cells (p = 0.007)." (PMID 39462876, 2025). "Therefore, CD1a+ cells in the PT region can play a central role in establishing the population of mature DCs in the tumor center of synchronous liver metastases, as evidenced by the high elasticity coefficient." (PMID 41410751, 2025). "Moreover, PD-L1 and -L2 are present on tumor-infiltrating DCs, especially CD1a+ subsets, potentially suppressing anti-tumor immune responses and aiding immune evasion in cSCC." (PMID 40868818, 2025). "A pathognomonic feature of BM involvement is the presence of CD1a-positive tumor cells." (PMID 39081692, 2024). "Since CD1a+ DCs mainly present non-peptide antigens to T cells, especially glycolipids, CD1a+ DCs play a significant role in presenting tumor-associated antigens." (PMID 39768204, 2024). "Immunohistochemically, the tumor cells were strongly positive for S-100, CD1a, and langerin." (PMID 39705477, 2024). "As the results of previous research focused on CD1a-DCs infiltration into regional LNs of other organs varied, the role and significance of CD1a-DCs infiltration in regional LNs may be different according to the tumor histology or its primary site." (PMID 39684473, 2024). "In addition to TILs, various cells of the innate immune system, such as macrophages, CD1a+ dendritic cells (DCs), and natural-killer (NK) cells, are part of the tumor microenvironment." (PMID 37345025, 2023). "Similarly, a high prevalence of IL-37+CD1a+ DCs in HCC tumor infiltration is a marker of favorable prognosis of patients." (PMID 37298214, 2023). "It was observed by Brunhuber that mature and CD1a+ DCs are present close to the tumor area and may interact with Paget cells." (PMID 37373062, 2023). "Moreover, there was a tendency towards more abundant CD1a+ DCs in distant area of tumor-free than in positive SLNs (63.25 ± 31.16 vs. 50.85 ± 29.46, p = 0.054)." (PMID 35955602, 2022). "Moreover, tumor cells have to stain positively for CD1a and S100 on immunohistochemistry to be identified as Langerhans cells." (PMID 35780646, 2022). "Notably, the density of mature DCs in the tumor mass was greatly reduced compared to that of CD1a+ iDCs." (PMID 35619702, 2022). "The average number of tumor-infiltrating CD1a+ DCs was 47 (range 1.3–351)." (PMID 34461859, 2021). "The tumor cells typically lack expression of CD1a, CD 68, and Desmin." (PMID 34596165, 2021). "Coventry and Heinzel had proposed a possible explanation for this observation as they hypothesized that CD1a is an important molecule for the presentation of glycolipid tumour antigens to the immune system." (PMID 33919875, 2021). "The histological tumour grade affected only the intratumoral CD1a+ cells counting for both quantification method (P=0.0258, SA method; P=0.0340, UA method), and the peritumoral CD1a+ cells counting for UA method (P=0.0232)." (PMID 32134901, 2020).
tumor (continued). "Interestingly, it has also been shown that tumor-derived prostanoids inhibit CD1a expression in DCs, even in the presence of TGF-β, further emphasizing the idea that PGE2 plays a defining role in the phenotype of DCs." (PMID 29988364, 2018). "Further IHC exams stated that elements such as positive markers for histiocytes and monocytes (CD68+++ and CD14+), Langerine- and CD1a – could exclude HCL or another tumor with dendritic undetermined cells, that are usually Langerine -, but CD1a+." (PMID 29450403, 2017). "Neither good pathological responders nor those whose tumours had a pCR with NAC had a significant association with pre-NAC CD1a+ TIDCs or CD66b+ TINs." (PMID 28913366, 2017). "CD1A positive cells mainly distributed in tumor and normal stroma around the normal epithelium." (PMID 26771842, 2016). "The area of the tumor tissue was calculated as the area of anti-CD1a staining in an FFPE section." (PMID 27094161, 2016). "Here, we test the hypothesis that specific candidate gene methylation markers (CCNA1, NDN, CD1A, DCC, p16, GADD45A) are associated with tumor recurrence and survival, in a well-characterized, prospective, cohort of 346 HNSCC patients." (PMID 26518708, 2015). "In addition, patients had twice the hazard of a tumor recurrence or persistence if they were at the 25th percentile of CD1A methylation compared to the 75th percentile." (PMID 26518708, 2015). "There is evidence that CD1a may be involved in the presentation of tumor specific glycolipids to T cells, inducing CD1a-restricted tumor-specific T-cell responses." (PMID 24088396, 2013). "The highest numbers of immature CD1a+ DCs were found within RCC tumour tissue." (PMID 20969772, 2010). "CD1a+ DCs within the tumour area and normal kidney tissue demonstrated co-expression for CCR6, whereas no expression for CCR7 could be observed as determined by immunohistochemistry and double-immunofluorescence studies." (PMID 20969772, 2010). "S100+ and CD1a+ DCs were found in tumor epithelium, in parallel with intraepithelial CD4+ or CD8+ T-cell infiltration and suggested increased disease-free survival, while HLA class II+ cells were observedin the stromal compartment, correlated with adversed outcome of the tumor." (PMID 19009040, 2008). "As emerging in the recent literature, CD1a has been regarded as a molecule whose expression may reflect tumour evolution." (PMID 15756258, 2005). "In our opinion, the present results may confirm that increased CD1a expression not only in DCs but above all in epithelial cells may prevent tumour progression, for instance regarding the evolution of GTBM towards Ca." (PMID 15756258, 2005). "Myeloid cells were subclustered into monocyte, Tumor-associated macrophage (TAM) including SPP1+ TAM, C1Qs+TAM, HSPs+ TAM, ACP5+ TAM, and CCL5+ TAM, classical dendritic cell (cDC) encompassing cDC, CD1A+ DC, LAMP3+ DC and PCLAF+ DC, plasmacytoid DC (pDC) as well as unknown subpopulations." (PMID 40904511, 2025). "As the varied results of previous studies, which mainly focused on CD1a-DCs infiltration into regional LNs of other organs, the role and significance of CD1a-DCs infiltration into regional LNs may be different according to tumor histology or the primary tumor site." (PMID 39684473, 2024). "On the other hand, presence of CD1a expressing cells in tumours may influence metastasis." (PMID 32565898, 2020). "Moreover, we suppose that CD1a expression may have an antitumoral role in BM mucosa, and also, as postulated, in neoplastic diseases arising at other anatomic sites." (PMID 15756258, 2005). "We identified opposing gradients of CD1a+ and CD208+ DCs consistent with an recruitment-maturation axis, with immature CD1a+ cells enriched in TC and mature CD208+ cells predominating in tumor exterior." (PMID 41410751, 2025). "Circulating monocytes are instead retained at the CD1a+ stage by GM-CSF, CXCL8, and CCL2 gradients in the primary tumor, turning the pCRC into a functional “monocyte reservoir”." (PMID 41410751, 2025).